FUS (FUS RNA binding protein)
Diseases named in the same sentence as FUS in open-access papers (continued):
Sharing a sentence is not in itself a finding about the gene and the disease.
motor neuron disease (35 papers, 2009 to 2025). "We also examined the effects of over-expression of mRNA that encodes for mutants of TDP-43 and FUS that cause motor neuron disease in humans." (PMID 28358904, 2017). "TDP-43 and FUS, RNA binding proteins linked to the motor neuron disease ALS, also contain disordered domains (green)." (PMID 27381259, 2016). "Histone deacetylase inhibitors have neuroprotective properties on their own that are relevant to our particular interest, motor neuron disorders, including the preservation of mutant FUS, a cause of familial ALS, in the nuclear compartment of cultured motor neurons as reported in the present study." (PMID 31900865, 2020). "Abnormalities in the nuclear pore complex have recently been described in ALS, and these defects may contribute to the abnormal subcellular localization of specific proteins linked to motor neuron diseases, such as fused in sarcoma (FUS), TAR DNA-binding protein 43 (TDP-43) and AR." (PMID 28087734, 2017). "While this informs our understanding of sporadic disease, it limits our contribution to the understanding of other motor neuron diseases, such as those related to mutations of SOD1, C9or72, or FUS." (PMID 40506843, 2025). "SG component proteins with a causal role for motor neuron diseases include TDP-43 (gene symbol TARDBP), FUS, ATXN2, SMN, Tau (gene symbol MAPT), HNRNPA2B1, and HNRNPA1." (PMID 24659297, 2014). "Mutations in RNA binding proteins such as Tar DNA binding protein-43 (TDP-43), Fused in sarcoma (FUS), survival of motor neuron (SMN1), ataxin-2 (ATX2), optineurin (OPT) and angiogenenin (ANG) all cause motor neuron diseases." (PMID 23164372, 2012). "Commensurate with these findings, motor neuron disease is induced by transgenic over-expression in rodents of human mutant FUS or TDP43, and by expression of wtTDP43 but not wtFUS." (PMID 22493728, 2012). "Similarly, mutations in FUS, HNRNPA1/B2, and other RNA-binding proteins have been associated with familial forms of motor neuron disorders." (PMID 37730840, 2023). "If there are no associated signs of motor neurone disease, this is highly unlikely to be an inherited mutation in the FUS gene." (PMID 33310885, 2020). "Given that RNA-binding proteins such as hnRNP A1, FUS, and TDP43 have been associated with snRNP biology and splicing defects in ALS motor neuron diseases, we asked whether they could be modulated by flunarizine at the protein level." (PMID 32363199, 2020). "In summary, our findings provide the molecular details of an RNA-based toxic gain-of-function of FUS in the cytoplasm causing a molecular defect that strengthens the link between FUS-linked ALS and SMA, with both motor neuron disorders displaying cytoplasmic snRNP biogenesis defects." (PMID 33311468, 2020). "Mutations in FUS, hnRNPA1/B2 and other RBPs are associated with familial forms of motor neuron disorders, while mutations in proteins associated with formation or removal of RNA granules cause ALS, FTLD, other motor neuron diseases as well as myopathies." (PMID 28420962, 2017). "In conclusion, we characterize here a heterozygous knock-in mouse model of ALS and demonstrate that mutations in FUS result in a toxic gain of function leading to motor neuron disease through cell autonomous and non-cell autonomous mechanisms." (PMID 28243725, 2017). "Finally, FUS pull down led to the identification of several interactors with known roles in motor neuron disease or other neurodegenerative disorders, including hnRNPA1, hnRNPA2B1, Matrin3 and FMRP." (PMID 27164932, 2016). "FUS mislocalization and accumulation in assembled SGs demonstrated here is consistent with previous studies of mutant human FUS sub-cellular localization in mammalian cell lines and supports the use of the zebrafish model for investigating the cellular physiology of FUS in motor neuron disease." (PMID 24912067, 2014).
motor neuron disease (continued). "The theme of altered RNA processing in motor neuron disease has been further emphasized by the recent discovery of roles for the RNA binding proteins TDP-43 (ALS10) and FUS (ALS6) in sporadic and familial ALS." (PMID 24244371, 2013). "Since ALS is a motor neuron disease we expressed wild type and mutant human TDP-43 and FUS proteins in the worm's 26 GABAergic motor neurons with the vesicular GABA transporter (unc-47) promoter." (PMID 22363618, 2012). "FUS knockout mice do not develop ALS-like symptoms or pathology, suggesting that loss of FUS function is not sufficient to cause motor neuron diseases." (PMID 33407930, 2021). "Wild-type FUS could rescue the Tardbp knockdown phenotype, but not vice versa, suggesting that TARDBP is upstream of FUS in this pathway responsible for motor neuron disorder." (PMID 21829392, 2011).
neuroblastoma (34 papers, 2012 to 2025). Neuroblastoma (NB) is the most common solid, extracranial childhood tumor. "Furthermore, at position 18S-Psi897 in neuroblastoma differentiated cells, FUS depletion and mutation resulted in higher pseudouridine levels." (PMID 36806717, 2023). "Moreover, the 18S-Gm436 position was sensitive to FUS depletion and mutation in neuroblastoma cells only." (PMID 36806717, 2023). "We also confirmed in human neuroblastoma cells SH-SY5Y that ALS-associated FUS mutants were deficient in regulating exon 7 repression in the context of the pDUP splicing reporter minigene, and that the deficiency correlated with the extent of cytoplasmic localization of the mutants." (PMID 24204307, 2013). "Consistent with the results of previous studies, GFP-tagged FUS variants rendered cytoplasmic by the introduction of mutations or truncations abrogating nuclear import were diffusely distributed in the cytoplasm of SH-SY5Y neuroblastoma cells or primary hippocampal neurons." (PMID 24842888, 2014). "Consistent with the findings in murine central nervous system tissue, a reduction in FUSint6&7-RNA was observed in human ALS-FUS cell models—FUSΔNLS SH-SY5Y (human neuroblastoma) lines generated by CRISPR-Cas9 editing to endogenously express FUS lacking NLS." (PMID 40700505, 2025). "Last, we showed that FUS mRNA and protein were down-regulated following exoFUSint7 overexpression in FUSΔNLS neuroblastoma cells." (PMID 40700505, 2025). "In this study, we developed a G4-focused version of RNA immunoprecipitation sequencing (G4 RIP-seq) using total RNA from SH-SY5Y human neuroblastoma cells and recombinant C-terminal FUS protein under G4-stabilizing and non-G4-stabilizing conditions." (PMID 41029441, 2025). "We observed synthetic toxicity in neuroblastoma cells co-expressing the mistranslating tRNA mutant and the ALS-causative FUS R521C variant." (PMID 36833445, 2023). "In our study, small RNA sequencing revealed that many C/D box snoRNAs, H/ACA box snoRNAs, and scaRNAs are differentially expressed in SH-SY5Y (neuroblastoma) FUS knockout (FUS KO) cells." (PMID 36806717, 2023). "To address this question, we employed the single-molecule pulldown (SiMPull) assay to measure the oligomerization status of FUS-RNA complexes in neuroblastoma cells (SH-SY5Y)." (PMID 37123224, 2023). "HuD was then found among the interactors of ALS-linked factors, including the RBPs Fused in sarcoma (FUS) and TAR DNA binding protein 43 (TDP-43), in neuroblastoma cells." (PMID 36498933, 2022). "In this work, we used acute and chronic stress paradigms to study the SG dynamics in a human SH-SY5Y neuroblastoma cell line carrying a deletion of the NLS domain of the FUS protein (homozygous: ΔNLS–/–; heterozygous: ΔNLS+/–)." (PMID 35002600, 2021). "FUS proteins with and without tails were expressed at a similar basal level, and CHX treatment of neuroblastoma cells for 36 h led to reduced FUS protein levels." (PMID 32404191, 2020). "Further, mouse neuroblastoma Neuro2a cells were transiently transfected with empty vector, wild-type FUS, or ΔNLS-FUS, and the intensity of puromycin was assessed by western blot analysis." (PMID 28928015, 2017). "We transfected mouse neuroblastoma (N2A) cells with V5-tagged wild type (WT), P525L or Y526C FUS constructs." (PMID 25299611, 2014). "A similar pattern was observed in COS7 cells, in neuroblastoma cells expressing dRGG3 and FUS 1–513, in cells transfected with Flag-tagged R522G FUS and upon treatment with another transcriptional inhibitor selectively targeting RNA polymerase II, DRB." (PMID 24842888, 2014). "After confirming that JSF1 could serve as a phase modulator for FUS, we investigated whether JSF1 could also regulate the biophysical states of FUS in the neuroblastoma 2 A (N2A) cell line." (PMID 38971830, 2024).
neuroblastoma (continued). "In the present work, we used the human SH-SY5Y neuroblastoma cells permanently transfected with FUS bearing a deletion of the C-terminus containing the nuclear localization signal domain (NLS) to study the effect of either acute or chronic stress on SGs formation and persistence." (PMID 35002600, 2021). "In fact, it has also been shown that siRNA-induced FUS downregulation in human neuroblastoma cell lines had tumor-suppressive effects, and the physical interaction of FUS with the long non-coding RNA NEAT1 promotes cell survival, while FUS reduction triggered apoptotic cell death in breast cancer." (PMID 34299185, 2021). "To address this, we constructed a panel of plasmids for the expression of ALS-linked truncated FUS proteins with or without respective frameshift peptide tails, and analysed their cellular distribution, levels and stability in human neuroblastoma cells." (PMID 32404191, 2020). "IP and GST pulldown SMN in HeLa nuclear extracts and mouse neuroblastoma (N2a) using FUS antibody." (PMID 31738166, 2019). "On the other hand, most in vitro studies with human cells rely on non-neural or neuroblastoma cell lines, in which mutated FUS or TDP-43 genes were overexpressed." (PMID 26035390, 2015). "In addition, 10 of the miRNAs that were differentially expressed in the SALS fibroblasts were also decreased in a neuroblastoma knockdown model of FUS; FUS expression has also been shown to be decreased in these fibroblasts." (PMID 24750211, 2015). "Briefly, we transfect SH-SY5Y neuroblastoma cells with WT or mutant FUS-GFP constructs for ∼24 h and gently lyse the cells with NP40 cell lysis buffer to maintain FUS complexes (see STAR Methods)." (PMID 37123224, 2023). "Consistent with data from neuroblastoma cells, paraspeckle numbers and NEAT1 positive area were increased ~ 2-fold in mutant FUS fibroblasts." (PMID 30642400, 2019). "Two independent FUS shRNAs were transfected into the neuroblastoma SH-SY5Y cell line and each shRNA induced ~70% depletion of FUS." (PMID 30206235, 2018). "To confirm a high aggregation propensity of the engineered FUS 1–359 protein in the cytoplasm of eukaryotic cells, we expressed it as a GFP fusion in the human neuroblastoma SH-SY5Y cell line." (PMID 23867462, 2013). "In turn, pseudouridylation at position 28S-Psi4579 was lower in HEK293T FUS KO cells but higher in FUS R495X cells, compared to WT, with no changes in neuroblastoma FUS KO cells." (PMID 36806717, 2023). "For example, the pseudouridylation status at site 28S-Psi5001 was significantly higher in HEK293T FUS KO and neuroblastoma FUS KO proliferating cells, while pseudouridylation status at site 28S-Psi2839 was increased in HEK293T FUS KO and neuroblastoma FUS KO and FUS R495X differentiated cells." (PMID 36806717, 2023). "Expression of green fluorescent protein (GFP)-tagged FUS protein with missense mutation FUSR521C or truncation mutant FUSR495X in the neuronal-like neuroblastoma cell line, SH-SY5Y, led to a significant increase in the fluorescence intensity of cytoplasmic FUS when compared to FUSWT." (PMID 34290285, 2021). "As FUS is a member of the TET protein family, this protein was found to be inversely regulated by miR-141 in human neuroblastoma and can be activated by lncRNA XIST, which also served as a ceRNA in cervical cancer progression while competitively binding with miR-200a." (PMID 32117463, 2020). "Activity of the constructs was measured in the human neuroblastoma cell line SK-N-AS, which was shown by RT-PCR to express endogenous FUS, data not shown." (PMID 24608899, 2014). "In this study, we explored the roles of G-quadruplex non-canonical secondary structures as a mechanism for FUS protein recognition and binding to its target RNAs in SH-SY5Y neuroblastoma cells." (PMID 41029441, 2025).
dementia (28 papers, 2012 to 2025). Loss of intellectual abilities interfering with an individual's social and occupational functions. "Recent studies have demonstrated that both compounds exhibit strong affinities for the FUS protein, indicating their potential to interact with and possibly inhibit FUS dysfunction, which is linked to dementia." (PMID 39975842, 2024). "Moreover, thanks to NGS approach, we disclosed other variants in dementia-related genes, in particular FUS, ABCA7, CSF1R, DCTN1, SERPINI1 and SORL1." (PMID 33006056, 2021). "Similarly, a significant increase in γH2AX levels was observed in frontal cortex tissue sample from patients with frontal temporal lobular dementia associated with FUS pathology when compared to controls (p = 0.001), along with accumulation of insoluble FUS protein." (PMID 41245603, 2025). "The broader implications of this research lie in the identification of plant-derived compounds with the potential to inhibit the FUS protein, opening new pathways for natural product-based drug development for dementia." (PMID 39975842, 2024). "In this study, we explored a computational approach to discover natural inhibitors for the FUS protein, a key target in neurodegenerative diseases such as dementia." (PMID 39975842, 2024). "By pinpointing compounds such as dehydroxymethylflazine and cleroindicin C that exhibit strong binding affinities and stable interactions with the FUS protein, we are pushing the boundaries of drug discovery in dementia." (PMID 39975842, 2024). "In one individual with AD and a known family history of dementia we found a Ser57 deletion (rs777545405) in FUS." (PMID 35120450, 2022). "No other pathogenic mutation in genes known to be associated with neurodegenerative diseases, and/or rare genetic causes of dementia, such as mutations in CHMP2B, FUS, TARDBP, SQSTM1 and VCP have been identified." (PMID 27632209, 2016). "FUS is a nucleic acid binding protein related to TDP-43 that has also been implicated in ALS and dementia and the expression of an ALS-linked FUS allele in C. elegans motor neurons produces degenerative phenotypes similar to mutant TDP-43." (PMID 22792076, 2012). "Interestingly in module-4, we found CDC5L connected with FUS protein, which is one of the high-risk proteins of both familial and sporadic type ALS, Dementia, and Parkinson’s disease." (PMID 34918006, 2022). "AS dysregulation in genes like MAPT (tau isoforms), TREM2 (microglial function), and RNA-binding proteins (TDP-43, FUS) underpins dementia but has never been systematically studied in AfrAbian cohorts." (PMID 40600167, 2025). "No pathogenic variants were identified in known dementia or ALS genes, including FUS on chromosome 16." (PMID 23338750, 2013). "FUS inclusions are not only observed in presence of FUS mutations, as they were found in patients with different or unknown genetic defects such as sporadic ALS, ALS/dementia or FTLD (with or without progranulin mutations), FUS or TDP43 mutation-linked familial ALS, SOD1-negative familial ALS." (PMID 25852467, 2015).
Parkinson disease (27 papers, 2012 to 2025). A progressive degenerative disorder of the central nervous system characterized by loss of dopamine producing neurons in the substantia nigra and the presence of Lewy bodies in the substantia nigra and locus coeruleus. "Patient 2, affected by LOAD with parkinsonism, harboured the Tyr239Cys variant in FUS, a gene implicated in ALS and FTD cases." (PMID 33006056, 2021). "The Fused-in-Sarcoma (FUS) gene, encoding the RNA-binding protein FUS, located on chromosome 16, is also implicated in FTD, and it is infrequently accompanied by parkinsonism." (PMID 40722695, 2025). "In neurodegenerative disorders like Parkinson's, Alzheimer's, and ALS, phenotypes were chiefly identified at the neuronal stage, with the exception of one iPS cell line with a mutation in PSEN1 and one line with mutant FUS." (PMID 29051230, 2017).
Huntington disease (26 papers, 2013 to 2025). Huntington disease (HD) is a rare neurodegenerative disorder of the central nervous system characterized by unwanted choreatic movements, behavioral and psychiatric disturbances and dementia. "In this study, we found that age-associated hyperactivation of EPS8/RAC signaling in Caenorhabditis elegans promotes the pathological aggregation of Huntington’s disease-related polyglutamine repeats and ALS-associated mutant FUS and TDP-43 variants." (PMID 40903652, 2025). "To determine whether the neuroprotective effect conferred by L. rhamnosus HA-114 was exclusive to TDP-43 or FUS pathogenesis or could be extended to other models of neurodegenerative diseases, we tested various models of age-associated neurodegeneration, including models of Huntington’s disease." (PMID 36477191, 2022). "Inefficient microtubule-based transport in axons is linked with several age-related neurodegenerative diseases including Alzheimer’s, Huntington’s disease, and hereditary spastic paraplegia, as well as with ALS caused by mutations in SOD1, TARDBP, and FUS." (PMID 33837088, 2021). "FUS has also been detected in aggregates found in other neurodegenerative disorders including FTLD, Huntington’s disease and SCA indicating that disruption of WT FUS function is associated with neurodegenerative disease in general." (PMID 23673820, 2013). "Mitochondrial transport deficits are linked with several neurodegenerative disorders, such as Alzheimer’s and Huntington’s disease, hereditary spastic paraplegia, Charcot–Marie–Tooth disease, as well as ALS with SOD1, TARDBP, and FUS mutations, and ALS with hexanucleotide repeats in C9orf72." (PMID 38363426, 2024). "Cytoplasmic inclusions of human FUS proteins are observed in various neurodegenerative disorders, such as Huntington’s disease or spinocerebellar ataxia, suggesting that FUS proteinopathy may be a key player in neurodegeneration." (PMID 34568776, 2021). "Furthermore, studies show that FUS strongly interacts with pathological neuronal intranuclear inclusions found in the brains of patients with Huntington disease (HD), spinocerebellar ataxia and dentatorubral-pallidoluysian atrophy." (PMID 30002616, 2018). "In addition, FUS is the major component of nuclear polyQ aggregates of Huntington disease (HD) as well as spinocerebellar ataxia type 1, 2, 3, and dentatorubral-pallidoluysian atrophy." (PMID 23941283, 2013). "We confirmed the association of endogenous UBL3 with the RNA-binding proteins FUS and HPRT1—both listed in the Neurodegenerative Diseases Variation Database (NDDVD)—and with LYPLA1, which is involved in Huntington’s disease, using immunoprecipitation (IP)-western blotting analysis." (PMID 39148092, 2024). "Both FUS and TAF15 were also detected in the detergent-insoluble fraction of the Huntington’s disease mice R6/2, indicating that TAF15 insolubility seems a secondary effect of FUS aggregation and is not due to exposure to injected FUS fibrils." (PMID 38862967, 2024).